VIM (vimentin)
Diseases named in the same sentence as VIM in open-access papers (continued):
Sharing a sentence is not in itself a finding about the gene and the disease.
infection (continued). "Our result showed that expression of SNAI1, N-cadherin and Vimentin was reduced in CoCl2-treated HCC cells after infection with Ad-shHIF1α, whereas E-cadherin was increased in CoCl2-treated HCC cells after infection with Ad-shHIF1α." (PMID 23496980, 2013). "Vimentin was reported to be phosphorylated at Ser82 and rearranged after infection of African swine fever virus infection." (PMID 24282534, 2013). "In MKN74 cells, ZEB1 starts rising at 6 hours post-infection independently on CagA, and the pri-miR-200b, E-cadherin and vimentin up-regulations were noticeable only at 24 hrs post-infection with the wt bacteria." (PMID 23565224, 2013). "The levels of ser 82 phosphorylated vimentin (ser 82-p vimentin) increased concomintantly with the time of infection." (PMID 24073199, 2013). "The obtained data have strongly indicated the important role of the cytoskeleton system in the progress of HPAI infection in chicken brain tissue as vimentin was significantly down regulated after infection." (PMID 22361110, 2012). "GBF1 inhibited cells were more sensitive to Triton extraction (data not shown), similar to what has been reported following disruption of the actin and vimentin cage during infection, suggesting that the cytoskeletal cage is compromised upon GBF1 inhibition." (PMID 21909260, 2011). "The picornavirus encephalomyocarditis virus (EMCV) further induces an autoimmune response against vimentin after infection." (PMID 19412526, 2009). "As demonstrated by increased mean fluorescence intensities, HIV-1/VSV infection of microglia increased expression of vimentin compared to uninfected microglia (n = 3, p<0.05)." (PMID 18575609, 2008). "In contrast, at 24 hours post infection, by which time there are substantial virus-induced changes in cell morphology almost all the vimentin and VP2 present in the cell colocalised." (PMID 17224050, 2007). "At 8 hours post infection vimentin was distributed throughout the cell but was also present in concentrated foci within the cytoplasm." (PMID 17224050, 2007). "Cytoskeletal vimentin sustains cellular structural homeostasis; It collaborates with microtubules and microfilaments to establish a comprehensive cellular lattice system, and is involved in modulating the infection processes of diverse viruses." (PMID 40880512, 2025). "Analyses of earlier time points (3 and 9 dpi) demonstrated a stepwise increase in the number of HER2+ cells and Ki67+ HER2+ cells after MA10 infection, with transient increases in EpCAM positivity and reductions in vimentin positivity, as observed after IAV infection." (PMID 40739350, 2025). "Since transendothelial migration is a crucial step in neutrophil extravasation at sites of infection or inflammation, we investigated the effects of vimentin on neutrophil migration in both transwell assays and a more physiologically relevant three-dimensional (3D) microfluidic endothelial model." (PMID 39910535, 2025). "Consequently, this study aims to elucidate the role of vimentin in the infection of keratinocytes by S. aureus, as well as the expression mechanisms triggered by the interaction between TLR2 present on the surface of HaCaT cells and S. aureus." (PMID 40061451, 2025). "The binding of vimentin to S. aureus accelerated the intracellular infection of HaCaT cells." (PMID 40061451, 2025). "These probiotics did not induce vimentin expression in HaCaT cells, suggesting a close association between vimentin and the intracellular infection of bacteria." (PMID 40061451, 2025). "In the current study, the EMT marker vimentin was detected in both the middle and late infection stages, and its expression levels were significantly higher in the infected group than in the uninfected group, indicating that E. granulosus can induce EMT in host livers." (PMID 39625960, 2024).
infection (continued). "To confirm whether the “detrimental” proteins enhanced SARS-CoV-2 infection, we conducted in vitro VeroE6 infection assays using purified recombinant VIM, SERPINC1, and S100A9 across the range of concentrations detected in the saliva." (PMID 38007005, 2024). "Moreover, others have shown that the pre-treatment of human papillomavirus (HPV) pseudovirus with endogenous vimentin delayed the infection of NIKS cells." (PMID 39057066, 2024). "Higher levels of vimentin in saliva could thus enhance viral uptake and contribute to the increased infection observed within our detrimental saliva subset." (PMID 38007005, 2024). "Several transmembrane proteases, including ADAM17, transmembrane serine protease 2 (TMPRSS), and tumor necrosis factor (TNF)-converting enzyme, along with proteins like vimentin and clathrin are believed to play roles in the comprehensive process of establishing infection." (PMID 38339115, 2024). "The delayed wound healing seen in both patients, which might be a consequence of the resultant decrease in vimentin expression, could also increase the chance of infection." (PMID 38928066, 2024). "The anti-vimentin antibody significantly reduced fibrin formation in post-infection plasma with a maximum absorbance (optical density) of 3.0 × 10–2 ± 0.015, mean ± SD (n = 3) compared with IgG isotype antibody with a maximum absorbance of 12.3 × 10–2 ± 0.015 mean ± SD (n = 3)." (PMID 39207603, 2024). "Therefore, to evaluate the impact of the host immune response’s strength on gut microbiota balance during infection, we chose vimentin gene knockout mice (vim−/− mice) and wild-type (WT) mice as experimental models." (PMID 38956725, 2024). "Importantly, there was noticeable colocalization between the rearranged vimentin filaments and viral dsRNA after infection with JS/7/05/Ch in the cytoplasm." (PMID 37848995, 2023). "Taken together, these findings indicate that vimentin is responsible for mediating various steps in the infection process of the velogenic variant NDV strain but not the mesogenic strain." (PMID 37848995, 2023). "Furthermore, more Vimentin positive FLSs and F4/80 positive macrophages were observed after CircReeb1 infection compared to the group that received DMM operation only." (PMID 37640697, 2023). "In addition, the envelope protein of dengue virus in endothelial cells interacted with the vimentin rod domain to promote virus absorption and subsequent infection." (PMID 37928675, 2023). "Moreover, viral internalization and fusion, important steps of infection following viral adsorption, can be regulated by vimentin." (PMID 37848995, 2023). "After infection for 28 and 42 days, the level of E-cadherin mRNA decreased, whereas the level of marker mRNA associated with EMT (N-cadherin, fibronectin, laminin, and vimentin) were increased significantly." (PMID 36828540, 2023). "Therefore, we conducted further assays to investigate the role of vimentin in the subsequent infection processes of genotype III NDV." (PMID 37848995, 2023). "M. tuberculosis is another pathogen that targets vimentin to favor infection." (PMID 37475865, 2023). "For instance, what is the impact of vimentin on the infection processes of other NDV genotypes?" (PMID 37848995, 2023). "The discrepancy suggested the possibility that Cdc42 may switch its preferred substrates between actin and vimentin, depending on specific pathogens, host cell types, and/or the time course of infection." (PMID 36717589, 2023). "To test this hypothesis, we conducted further investigation into the effects of vimentin during different stages of infection in HD11 cells." (PMID 37848995, 2023). "The phosphorylation levels of vimentin at Ser6 and Ser7 sites were significantly higher than those of the uninfected cells 6 h and 36 h after infection by sporozoites, while the phosphorylation level at Ser 4 sites was significantly lower 36 h after infection than after 6 h (unpublished data)." (PMID 34983604, 2022).
infection (continued). "Even less understood is the observation that the intermediate filament protein vimentin enhances infection after endosomal escape as shown for MVM (Fay & Panté, 2013) as intermediate filaments are not polarized and thus hardly contribute to directed cytoplasmic transport." (PMID 35974704, 2022). "Host vimentin is a key protein in the process of infection of many pathogens." (PMID 34983604, 2022). "The changes in vimentin expression levels differed among different pathogen infections, which suggests that vimentin may play different roles in different pathogen infections." (PMID 34983604, 2022). "Infection then induces vimentin rearrangement, which is closely related to Ser71 phosphorylation." (PMID 35433510, 2022). "Vimentin phosphorylation peaked 12 h after infection and subsequently decreased." (PMID 35433510, 2022). "Besides these complex biological functions, vimentin is expressed on the cell surface and acts as a receptor to interact with the proteins of pathogens, regulating the pathogen infection process in host cells." (PMID 34983604, 2022). "Total vimentin levels decreased obviously 24 h after infection." (PMID 35433510, 2022). "In addition to its participation in infection, VIM also plays a critical role in lung inflammation and fibrosis through interaction with NLRP3 (NACHT, LRR, and PYD domains-containing protein 3)." (PMID 35078919, 2022). "In conclusion, our data demonstrate that VIM is required for robust infection of endothelial cells by SARS-COV-2 and suggest that VIM could be a target for preventative or therapeutic intervention." (PMID 35078919, 2022). "Surface vimentin can facilitate internalization of virus and bacteria and infection of cells." (PMID 34198868, 2021). "Moreover, in BC cells, the protein levels of miR-141-3p infected with c-myc and Vimentin were mainly restrained by miR-141-3p + AK2 infection." (PMID 34887922, 2021). "According to the multifunctional role of vimentin in pathogen infection, we hypothesized that vimentin may play a role in the response to RHDV infection and the course of RHD, which could be a potential target in antiviral strategies." (PMID 34372621, 2021). "While vimentin was supplied artificially in this study to assess its effect on HPV-PsVs infection, secreted extracellular vimentin has been described in response to various physiological conditions in vitro, such as inflammation, senescence, stress and cellular activation." (PMID 34960740, 2021). "Infectious agents can also modulate vimentin to facilitate infection." (PMID 32630064, 2020). "Here, we wanted to determine whether Hsp70 and Hsp90 had any role in vimentin dynamics during infection." (PMID 31619557, 2020). "Inhibiting vimentin dynamics delays host cell death while allowing efficient infection." (PMID 31619557, 2020). "Furthermore, murine hookworm antigen exposure and in vivo infection decreased expression of cell surface vimentin or total vimentin expression in the cell line or the FRT, respectively." (PMID 33329545, 2020). "The knock-down of vimentin reduced the number of C. burnetii at 4 h post-infection." (PMID 33282747, 2020). "Also, vimentin protein was related with pH-dependent infection of parvovirus, dengue virus replication and release." (PMID 32552884, 2020). "Indeed, the luminal endoplasmic reticulum (ER) marker PDI was spread out during IDPN treatment, while during infection it was drawn to the vimentin cage area, colocalizing with dsRNA." (PMID 31619557, 2020). "These cells may be derived from another undefined cluster (C4) that has some SOX2 and VIM expression and also shows a modest proportional decrease in cell number with infection." (PMID 31739796, 2019). "For example, vimentin is down regulated in macrophages infected with Mycobacterium tuberculosis, contributing to increased replication and persistence of the pathogen within these cells, confirming the importance of vimentin in host cell response to infection." (PMID 30699149, 2019).
infection (continued). "While the infection of vimentin-knockout MEFs (a cell line also deficient in cytokeratins) produced F-actin rings comparable to the infection of wild-type cells, these rings lacked the highly compact and ordered morphology of their wild-type counterparts." (PMID 31877733, 2019). "Moreover, the decreased range of viral attachment, replication, protein synthesis, and secretion in the EV-A71-289A infection was larger than that in the EV-A71-289T infection upon VIM-KO." (PMID 31121933, 2019). "Thus, vimentin has been shown to be important in experimental models of infection at body sites other than the brain." (PMID 31181121, 2019). "Moreover, in both EV-A71-289A and EV-A71-289T infections, viral RNA levels in control HBMECs were greater than those in VIM-KO HBMECs." (PMID 31121933, 2019). "Additionally, we found that BspC and vimentin contribute to the development of GBS meningitis in a mouse infection model." (PMID 31181121, 2019). "Activation of inflammasomes by VIM was also observed in mice with an EV-A71 infection." (PMID 31121933, 2019). "Surface vimentin has also been suggested to promote infection by binding to dengue virus." (PMID 30248895, 2018). "In addition, we show that the intracellular pathogen Chlamydia trachomatis, which remodels the host IF cytoskeleton during infection, requires specific vimentin glycosylation sites and O-GlcNAc transferase activity to maintain its replicative niche." (PMID 29513221, 2018). "In line with this, we observed a massive accumulation of cellular vimentin during infection." (PMID 28634388, 2017). "Likewise, infection as measured by luciferase activity was significantly increased when vimentin expression was reduced, which was more pronounced when the particles were not pretreated with furin." (PMID 28566373, 2017). "Interestingly, vimentin surface levels slightly increased over time upon infection with the viral particles; however, furin-precleaved and untreated particles had a comparable effects." (PMID 28566373, 2017). "Ten weeks post-22 L infection, we detected astrogliosis by means of vimentin and GFAP expression." (PMID 29126445, 2017). "Productive infection by two additional ZIKV strains, Puerto Rico 2015 (PRVABC59) and Thailand 201326, was observed in primary HESC by a plaque forming assay (PFA) 3 days post-infection, with intracellular co-localization of the E protein and dsRNA with calreticulin and vimentin, respectively." (PMID 28281680, 2017). "Viruses require cytoskeletal proteins for viral entry and establishment of infection, and the disruption of vimentin might block virion assembly and budding." (PMID 28097424, 2017). "We further demonstrated that both furin-precleaved and uncleaved HPV16-PsVs colocalized with surface-expressed vimentin on pgsD677, HeLa, HaCaT, and NIKS cells, while binding of incoming viral particles to soluble vimentin protein before infection led to a substantial decrease in viral uptake." (PMID 28566373, 2017). "Vimentin assembly around the ApV early during infection is important for its optimal formation and bacterial intracellular growth, a finding that is in agreement with a report that vimentin assembly at the ApV mediated by the effector, AptA, activates Erk/MAPK to promote A. phagocytophilum survival." (PMID 29056733, 2016). "Given the pronounced localization of vimentin at the ApV that is maintained throughout infection, we rationalized that this might be important for optimal A. phagocytophilum growth." (PMID 29056733, 2016). "Histological examination of brain sections with hematoxylin-eosin staining indicated that the blood infiltration into brain cortex and neuronal injury in the dentate gyrus of the hippocampus induced by E44 infection were both decreased in vimentin knockout by IbeA deletion (ZD1)." (PMID 27657497, 2016). "However, this study suggested that CPAF plays a role late in infection and that CPAF-mediated vimentin proteolysis correlates with a loss of inclusion membrane integrity." (PMID 27096872, 2016).
infection (continued). "The effect of CTSB and vimentin to viral protein expression were confirmed by HCV JFH1 infection." (PMID 26544179, 2015). "AdHNF4α infection of primary hepatocytes that had been treated by TGFβ1 for 48 h decreased miR-21 levels, along with a significant reduction in the mRNA transcript levels of vimentin and a noticeable increase in the mRNA transcript levels of E-cadherin." (PMID 25303175, 2014). "In addition, levels of epithelial markers plakoglobin and E-cadherin were enhanced along with the decreased expression of mesenchymal markers N-cadherin and vimentin in SC-M1 cells after infection with miR-34a- or miR-34bc-expressing adenoviruses." (PMID 24970812, 2014). "The upregulation of vimentin in response to C. burnetii infection suggests that the monocytes are being activated after infection to become macrophages and may have started differentiating at 96 hours postinfection." (PMID 23990884, 2013). "Chicken Vimentin was found to be down regulated in brain during infections with HPAI H5N1." (PMID 22361110, 2012). "It will be important to determine whether the alterations in the actin and vimentin cytoskeleton during infection are directly or indirectly modulated by GBF1." (PMID 21909260, 2011). "Several other bacterial and viral pathogens use surface vimentin as an attachment receptor as well, and this research may lead to the development of broad-spectrum strategies to inhibit infection." (PMID 19412526, 2009). "Therefore, elucidating the role of vimentin in the infection of keratinocytes by S. aureus may enhance our understanding of immune evasion strategies and the pathogenesis of skin commensals, including S. aureus." (PMID 40061451, 2025). "Moreover, additional receptors might be involved in this complex entry process, particularly in the context of Marc-145 cells, where simian vimentin and CD151 have been implicated as potential contributors to PRRSV entry and infection." (PMID 40146709, 2025). "However, upon infection with S. aureus, vimentin levels increased for up to 6 h before declining." (PMID 40061451, 2025). "Given that the DMSO‐differentiated hepatocytes are non‐dividing and in close contact with adjacent cells in which HCV tends to utilize cell–cell transmission for propagation, we hypothesize that vimentin may participate in HCV cell–cell transmission instead of conventional cell‐free infection." (PMID 39611409, 2025). "Therefore, we tested whether the elevated vimentin observed in septic piglets was capable of markedly influencing fibrin structures in post-MRSA plasma samples compared to pre-infection." (PMID 39207603, 2024). "Additionally, we found that the infection may induce migration or suppress cellular migratory properties and migratory markers (i.e., VIM and MMP9)." (PMID 39427065, 2024). "Interestingly, soluble vimentin can be used to prevent infection." (PMID 39057066, 2024). "Notably, the robust interaction between the prototypic HN and vimentin may weaken the impact of vimentin on these infection processes." (PMID 37848995, 2023). "Vimentin knockdown led to a notable reduction in the viral titre specifically in the supernatant of JS/7/05/Ch-infected cells from 6 to 24 hpi (p < 0.001), whereas no significant decrease in the viral titre was observed in the supernatants of other infected cells during infection (P > 0.05)." (PMID 37848995, 2023). "However, the role of vimentin rearrangement in pathogen infection is unclear." (PMID 34983604, 2022). "Furthermore, vimentin null mice were protected from infection by intranasally administered SS2." (PMID 35921364, 2022). "VIM is expressed in lymphocytes and can interact with other proteins for intercellular signal transduction and can be released as an antigen component of pathogen infection, with bacterial and viral pathogens able to attach to this protein on the host cell surface." (PMID 35092700, 2022).